PIEZO1P2 (piezo type mechanosensitive ion channel component 1 pseudogene 2)
Gene: Transcribed unprocessed pseudogene on chromosome 20 (58,740,532 to 58,783,821, reverse strand). Ensembl gene ENSG00000237121.
Diseases named in the same sentence as PIEZO1P2 in open-access papers:
PIEZO1P2 is named in the same sentence as 1 disease in open-access papers, as found by Europe PMC text mining. Sharing a sentence is not in itself a finding about the gene and the disease. The quoted sentences say what the papers report.
Obesity (1 paper, 2019). Accumulation of substantial excess body fat. "Given these convergent lines of research, PIEZO1P2 and its regulatory regions should be treated as targets of obesity-related research." (PMID 30918249, 2019).